BACE1 (beta-secretase 1)
Diseases named in the same sentence as BACE1 in open-access papers (continued):
Sharing a sentence is not in itself a finding about the gene and the disease.
dementia (continued). "Neurogranin and BACE1 level differences remained stable over time not only within A/T/N groups but also in patients progressing to more pathological A/T/N stages (e.g. progressing from A+/T−/N− to A + T or N+) and in cases progressing to dementia." (PMID 36262371, 2022). "Various studies have proposed BACE1 as a potential AD- and dementia-specific biomarker." (PMID 35402415, 2022). "Our work might provide a clue for dementia-relevant BACE1 modulation through exosome-mediated delivery of miRNAs to the endosomal system in the target neuron cells." (PMID 36497090, 2022). "Recent studies have also used blood BACE1 as a predictive marker for AD and dementia." (PMID 35402415, 2022). "After the confirmation of BACE1 and GFAP expressions in the hippocampus, we assessed if both proteins presented association by co-immunoprecipitation, how it had been reported previously and if presented differential association between dementias." (PMID 34025357, 2021). "Last but not least, BACE1 showed to perform even better in discriminating VAD from Controls when compared to MIXED dementia and LOAD (diagnostic accuracy values: 0.831, 0.772, 0.771, respectively)." (PMID 32917964, 2020). "The evidence that a pathogenic APP mutation causes an early enhancement of BAD‐Glu suggests that alterations of BACE1 processing of APP in glutamatergic synaptic vesicles could contribute to dementia." (PMID 31496118, 2019). "However, our data led us to hypothesize that BACE1 might have a role in dementia that is far beyond its significance as possible biomarker." (PMID 32917964, 2020). "Here, we have studied the expression of BACE1 in the hippocampi from AD patients at two stages of the disease: Braak II (one of the initial stages showing the early symptoms of AD) and Braak VI (the final stage of the disease, when the Aβ is widespread in the brain and dementia is severe)." (PMID 33014268, 2020). "Interestingly, mTBI did not affect BACE1 expression in wild-types, which supports the hypothesis of a predisposing effect, which in itself, under a WT genotype, is not sufficient to develop dementia, at least from a molecular point of view." (PMID 38992700, 2024). "All these previous studies are in concordance with our current data, confirming the interaction of BACE1 and SCD1 in human dementia brains." (PMID 37744400, 2023). "Despite this gender gap, the difference in BACE1 activity between Controls and LOAD, VAD or MIXED dementia was similar in women and men." (PMID 32917964, 2020). "In conclusion, we have demonstrated for the first time that BACE1 serum activity is increased in VAD and MIXED dementia as much as in LOAD, compared with healthy Controls; this increase is significant and is independent of possible measured confounders." (PMID 32917964, 2020). "Interestingly, BACE1 IP suggests a potential molecular complex or at least a coaggregation between SCD1, PHF-tau, cPLA2, and BACE1, which are markedly amplified in dementia cases compared to the control samples." (PMID 37744400, 2023). "Not only the APP gene is responsible for dementia in DS, GATD3A, SOD1, ERG, BACE2, DSCR1/RCAN1, APOE (19q13.32), BACE1 (11q23.3), IL1B (2q14.1), GSAP (7q11.23), UBB (17p11.2), and IRS1 (2q36.3) genes may also play a major role in dementia in DS." (PMID 35676933, 2022). "Although we did not observe changes between dementia cases by immunoprecipitation, it was clear by confocal microscopy that BACE1 was overregulated mainly in astrocytes on FAD and SAD groups, with a particular association with vessels in SAD." (PMID 34025357, 2021). "Additionally, neuron-specific, low expression of human beta-secretase BACE1 (PLB4 mice) also led to systemic diabetes, further confirming that brain-specific, dementia-relevant pathologies can dramatically affect systems physiology." (PMID 31396860, 2020).
dementia (continued). "On the contrary, patients with other forms of dementia (such as Lewy body disease, frontotemporal, etc.)did not exhibit a significant alteration in BACE1 activity." (PMID 32917964, 2020). "We are aware that our cross-sectional findings do not allow to precisely define the role of BACE1 in dementia pathogenesis." (PMID 32917964, 2020). "Bace1 cleavage of APP is activated by synaptic activity and generates the β-CTF APP metabolite that exerts a pathological role in mouse models of dementia." (PMID 25247712, 2014). "The lack of increase in CSF BACE1 activity or sAPPβ levels in cases with SAD dementia compared to healthycontrols is in agreement with most recent studies." (PMID 23224319, 2013). "Moreover, ulcerative colitis was recently linked to dementia, but the potential role of the presenilin 1(PS1)/BACE-1/beta-amyloid (Aβ) axis has not been evaluated." (PMID 36386153, 2022). "Therefore, considering the pathological connection with Aβ deposition and the significant correlation with the clinical symptoms of dementia, ADAM10 and BACE1 could serve as peripheral platelet biomarkers for early diagnosis of AD." (PMID 33942972, 2021). "We aimed to investigate whether BACE1 serum activity is altered also in dementias related, or not, to cerebrovascular disease." (PMID 32917964, 2020). "On the contrary, BACE1 activity was not increased in other forms of dementia." (PMID 32917964, 2020). "Inhibition of BACE‐1 by low‐molecular‐weight compounds has emerged as a new concept for treatment of AD by preventing the generation and deposition of Aβ rather than just treating the dementia symptoms." (PMID 30224383, 2018). "Interestingly, both BACE1 protein and activity levels can be measured in CSF, but, to date, accurate determination of BACE1 remains a great challenge and there is no consensus as to whether its levels are consistently affected in CSF as dementia progresses." (PMID 26082753, 2015). "BACE1 levels were significantly increased in AD and MCI-AD compared to non-AD MCI, other dementias, and controls." (PMID 32690068, 2020). "The goal of this study was to assess CSF NRG1 levels and BACE1 concentrations in AD, MCI-AD, non-AD MCI, other dementias, and neurological controls and to compare these results with usual CSF AD CSF and synaptic biomarkers and cognition in the same groups." (PMID 32690068, 2020). "However, the crucial role of BACE1 in NVU integrity and its implication on dementia has not detailed explored." (PMID 34025357, 2021). "We found that BACE1 was significantly higher not only in LOAD (+ 30%), but also in VAD (+ 35%) and MIXED dementia (+ 22%) (p < 0.001 for all), but not in the other types of dementia (+ 10%)." (PMID 32917964, 2020). "Compared with Controls, serum BACE1 activity was significantly higher in LOAD (+ 30%), VAD (+ 35%) and MIXED dementia (+ 22%) (p < 0.001 for all post-hoc comparisons), but not in the Other Dementias group (+ 12%; p > 0.10)." (PMID 32917964, 2020).
cognitive decline (61 papers, 2014 to 2026). "This review provides an overview of BACE1 mechanism as a dual disease-modifying therapeutic target to mitigate β-amyloidosis and insulin resistance that underlie cognitive decline at the intersection between AD and DM." (PMID 41446639, 2025). "In AD, S6K1 contributes to amyloid and tau pathology by regulating translation of BACE1 and tau, and its hyperactivation is linked to synaptic deficits and cognitive decline." (PMID 40649702, 2025). "Hypomethylation of these enhancers in AD is associated with an upregulation of BACE1 transcripts and an increase in amyloid plaques, neurofibrillary tangles, and cognitive decline." (PMID 40362435, 2025). "In fact, a polymorphism in APP that reduces APP processing by BACE1 protects humans from sporadic AD and normal aging-dependent cognitive decline." (PMID 25247712, 2014). "Oxidative stress may also influence beta-secretase 1 (BACE1), which has been linked to cognitive decline." (PMID 39238929, 2024). "In addition, GSI and BACE1 inhibitors exacerbated cognitive decline compared with placebo and were associated with an increased risk of AEs and SAEs." (PMID 38020763, 2023). "In agreement with the hypothesis that higher levels of serum BACE1 are related to a worsening of the cognitive functions, we found a positive association of cognitive decline with increased levels of serum BACE1." (PMID 35275540, 2022). "Second, a mutation in human APP, which reduces cleavage by BACE1, leads to a reduction in cerebral Aβ of approximately 20%, with carriers showing lifelong protection against AD and cognitive decline (although issues with the mutation affecting aggregation of Aβ peptides cannot be fully excluded)." (PMID 35352880, 2022). "Therefore, other BACE1 substrates are implicated in this effect and, potentially, in the cognitive decline in longer-term chronically treated patients." (PMID 34302009, 2021). "Impairments in cerebral metabolism have been linked to cognitive decline in AD, thus, the role of BACE1 in metabolic regulation and the diabetic phenotype observed in the PLB4 hBACE1 knock-in mouse model may contribute to memory impairment." (PMID 32867761, 2020). "As BACE1 partial inhibition may help in reducing Aβ load to rescue patients from cognitive decline, the development of BACE1 inhibitors that cause partial BACE1 inhibition is required." (PMID 31547430, 2019). "The relationship between IL-6, BACE1, and cognitive decline underscores the central role of neuroinflammation in disease progression." (PMID 40748886, 2025). "This elevated BACE-1 activity suggests a shared molecular pathway between T2DM and AD, potentially explaining the higher risk of cognitive decline and neuronal dysfunction observed in T2DM patients, as Aβ accumulation is central to both conditions." (PMID 39766390, 2024). "Previous studies have indicated that PCSK9 disrupts brain cholesterol homeostasis, cellular apoptosis, BACE1 expression, and Aβ generation, potentially leading to cognitive decline." (PMID 39157774, 2024). "Increasing evidences show the potential of serum/plasma BACE1 levels as an early biomarker of cognitive decline." (PMID 35275540, 2022). "The NGR/BACE1 ratio also showed potential prognostic value since individuals with higher concentrations had a more severe cognitive decline at follow-up." (PMID 33066807, 2020). "We showed that TCA inhibited Aβ deposition by modulating the expression of BACE1 in the 5XFAD mice, thereby inhibiting cognitive decline." (PMID 32599846, 2020). "It has been reported that BACE1 knockout (BACE1-/-) prevents the development of AD pathologies and cognitive decline in mouse models of AD." (PMID 29740283, 2018). "Caffeine, which modulates beta secretase (BACE)-1 and A2A receptors, has shown potential in preventing cognitive decline, though the optimal dosage for neuroprotection remains unclear." (PMID 40077790, 2025).
cognitive decline (continued). "Both BACE1 expression and γ-secretase components, including presenilin-1, are upregulated in the hippocampus and cortex within 24–72 h of injury, and their inhibition reduces Aβ accumulation and cognitive decline." (PMID 41009808, 2025). "The Icelandic mutation protects from AD (and from aging-associated cognitive decline, AACD) by increasing the efficiency of the cleavage by BACE1 or BACE1-associated activity at the alternative site (β’) ten amino acids residues downstream from the primary BACE1-cleaving site (β)." (PMID 38892224, 2024). "We find this hypothesis intriguing because the BACE1 inhibition–mediated cognitive decline in patients with AD is reversible." (PMID 36260691, 2022). "Moreover, in the MCI stage BACE1 correlated with disease progression as measured by cognitive decline." (PMID 35275540, 2022). "The clinical significance of cognitive decline in atabecestat treatment groups relative to placebo is unclear, but similar results favoring placebo were reported with other BACE1 inhibitors such as verubecestat in phase 3 trials for prodromal AD and mild-to-moderate AD." (PMID 32410694, 2020). "This hypothesis was later supported by the data indicating that the A673T substitution in APP, located adjacent to the BACE1 cleavage site and making the APP a less favorable substrate for BACE1, protects against cognitive decline and AD." (PMID 29636850, 2018). "These terminations again signaled that significant challenges are remaining: whether BACE1 inhibitors will be safe in the long run and if lowering BACE1 activity will slow cognitive decline." (PMID 25136630, 2014). "BACE1, implicated in AD pathogenesis, through APP cleavage and Aβ formation, was also associated with triglycerides, TG:HDL, and VAI, suggesting lipid levels may influence its activity and contribute to mechanisms of cognitive decline." (PMID 40665476, 2025). "In the carriers of this mutation, the β’-site cleaving activity of BACE1 (the prime target of the ACH2.0-base drugs) is significantly enhanced, yet the only effect these individuals are experiencing is beneficial: protection from both AD and aging-associated cognitive decline." (PMID 38892224, 2024). "This method could further be modified and applied to study the metabolism of non-APP BACE1 substrates, that have been implicated in chronic adverse events, such as cognitive decline, reported in Phase III BACE1 inhibitor clinical trials." (PMID 36056033, 2022). "We conclude that in an early AD stage characterized by low Aβ-accumulation and no irreversible spine loss, BACE1-inhibition could hold the progressive synapse loss and cognitive decline by improving structural spine dynamics." (PMID 35936777, 2022). "Indeed, experimental studies indicate that BACE1 activity significantly increases over time while its expression levels are less likely to be altered during cognitively healthy aging as well as in the presence of AD-related cognitive decline." (PMID 33066807, 2020). "By modulating APP processing, BACE1 expression, and autophagic clearance, S6K1 inhibition emerges as a promising therapeutic strategy for reducing Aβ accumulation and rescuing cognitive decline in AD." (PMID 40649702, 2025). "CaN, activated by calcium/CaM binding or calpain-mediated cleavage, enhances BACE1 expression through NFAT signaling promoting excitotoxicity and neuroinflammation, whereas inhibition reduces Aβ pathology and cognitive decline." (PMID 41009808, 2025). "We evaluated that 1) serum BACE1 activity increases in AD, 2) it increases at an earlier stage as in MCI-AD, 3) it can detect cognitive decline before AD diagnosis with high sensitivity and specificity, and 4) it performs better than the serum Aβ assay." (PMID 35275540, 2022). "SIRT2 regulates BACE1 by deacetylating RTN4B, which, in turn, influences Aβ production and aggregation, ultimately alleviates the cognitive decline of AD." (PMID 32700357, 2020).
cognitive decline (continued). "While the negative association between bace-1 methylation and amyloid load in persons with AD dementia was driven by cg16822189, the positive association between bace-1 methylation and both PHFtau tangle density and cognitive decline was driven by cg17007365, independent of the clinical diagnosis." (PMID 27681803, 2016). "In further support of this interpretation, BACE1 inhibitor treatments also failed to prevent cognitive decline in humans with AD." (PMID 33833046, 2021). "Taken together, these results indicated that gain-of-function of miR-195 rescued cognitive decline of APP/PS1 mice that related to preventing the increase of APP expression but not affecting BACE1 level." (PMID 33981225, 2021). "Aβ is not detected in BACE1 gene knockout mice, and the injection of a small interfering RNA targeting BACE1 into the mouse ventricle reduces the Aβ deposition and cognitive decline in APP transgenic mice." (PMID 31570097, 2019). "Imbalances between BACE1 and ADAM10 protein expression and enzyme activity where BACE1 is higher than ADAM10 may result in increased production and accumulation of Aβ peptides which can progress to cognitive decline and neurodegeneration." (PMID 39711362, 2025). "Although there have been no clinical trials on AOs targeting BACE1, six BACE1 inhibitors entered previously into clinical trials have failed due to liver toxicity in some cases and in others due to lack of improvement in cognitive decline." (PMID 31547430, 2019). "Since several mutations within the APP sequence have been shown to have an impact on BACE-1 cleavage affinity on APP, we analyzed a recently described APP mutation A673T that has been shown to protect against AD as well as against cognitive decline in the elderly independent of AD." (PMID 26895626, 2016). "Because the J20 model shares many features with AD patients, in which BACE1 inhibitors also failed to prevent or slow cognitive decline, the inability of BACEi to reduce functional abnormalities in J20 mice could be interpreted as high predictive value of the model." (PMID 32921309, 2020). "However, so far pharmacological BACE1 inhibition failed to rescue the cognitive decline in mild-to-moderate AD patients, which indicates that treatment at the symptomatic stage might be too late." (PMID 29327084, 2018). "Moreover, a single amino acid substitution adjacent to the BACE1 cleavage site of APP, which significantly reduces BACE1 cleavage and Aβ peptide generation in cultured cells, has been recently found to protect against disease onset as well as cognitive decline in the elderly without AD." (PMID 24386896, 2014).